GSTP1 (glutathione S-transferase pi 1)
Diseases named in the same sentence as GSTP1 in open-access papers (continued):
Sharing a sentence is not in itself a finding about the gene and the disease.
asthma (55 papers, 2007 to 2025). "This study identified significant associations between childhood asthma susceptibility and multiple SNPs in key antioxidant genes (GSTP1, HMOX1, and CAT), suggesting their potential utility as predictive biomarkers." (PMID 40433469, 2025). "Specifically, the GSTP1 rs1695 G allele conferred increased asthma risk, whereas the CAT rs769217 T allele exhibited protective effects." (PMID 40433469, 2025). "The age-stratified analysis showed that the asthma risk effects of GSTP1 rs1695, rs4891, CAT rs7943316, and HMOX1 rs17878790 were more significant in the >6-year-old group." (PMID 40433469, 2025). "Studies focusing on the impact of ozone exposure have corroborated that polymorphisms in oxidative stress genes, such as NQO1, GSTM1, and GSTP1, can precipitate respiratory symptoms and elevate the risk of asthma development." (PMID 39316602, 2024). "The most studied GST gene in relation to lung function and asthma outcomes is GSTP1, but the evidence for GSTP1 risk alleles is inconsistent." (PMID 36250015, 2022). "GSTP1 with Val/Val alleles were associated with decreased risk of asthma compared to those with Ile/Ile (OR 0.31, 95%CI 0.14, 0.69)." (PMID 36250015, 2022). "Influence of GSTP1 polymorphisms on the relationship between household environmental exposures and asthma and lung function." (PMID 36250015, 2022). "As GSTP1 with Ile/Ile genotypes has the highest enzyme activity, carriers of GSTP1 with any Val alleles would be expected to have a higher risk of asthma symptoms and poorer lung function." (PMID 36250015, 2022). "GSTP1 Val/Val was associated with decreased risk of asthma compared to Ile/Ile (OR: 0.14, 95% 0.05, 0.36)." (PMID 36250015, 2022). "Some studies have provided evidence that GSTP1 with Val alleles is associated with increased risk of asthma/wheeze outcomes in childhood with exposure to in-utero smoking." (PMID 36250015, 2022). "Meanwhile, there were five different genes that were consistently downregulated in ciliated cells following Tet1 loss and/or HDM treatment, including the asthma-associated genes Gstp1, Gstm1, and Gpx2." (PMID 35627266, 2022). "Specifically, in asthma, homozygosity of the GSTP1 Val105 allele is associated with reduced risk of airway hyperresponsiveness and improved lung function." (PMID 34988113, 2021). "Another study in 1124 schoolchildren aged 7–12 years described that SHS-exposed children with the GSTP1 polymorphism AA (Ile105Ile) at nucleotide 1695 showed an increased risk of asthma, too." (PMID 32380770, 2020). "In a study at 504 children and adolescents with asthma aged between 3 and 21 years, children exposed to SHS and with the GSTP1 polymorphism GG (Val105Val) at nucleotide 1695 or null for the GSTM1 gene were more prone to asthma." (PMID 32380770, 2020). "As it is now well indicated in different studies that GSTP1 genotypes and polymorphism have important roles in asthma pathogenesis." (PMID 30872977, 2019). "Several population studies connected genetic variation in human GSTP1 with greater susceptibility to asthma and the severity of signs." (PMID 30872977, 2019). "Among children exposed to NO2, those with either a GSTP1 rs1138272 or rs1695 single nucleotide polymorphism (SNP) were found to be at an increased risk for asthma in a study combining multiple birth cohorts." (PMID 30631772, 2018). "These include exposures such as PM10, PM2.5, ozone and NO2 and effects associated with altered asthma outcomes in those with particular single nucleotide polymorphisms in genes such as GSTP1, NQO1 and GSTT1." (PMID 29157272, 2017). "Only the marginal genetic association between GSTP1 rs1138272 and asthma was significant in the pooled TAG analysis." (PMID 29246113, 2017). "A significant different effect of genotypes was found among asthma cases and controls for GSTP1 (rs1695) and SOD2 (rs5746136) polymorphisms; however, only the effect of SOD2 survived the penalty for multiple testing." (PMID 28208751, 2017).
asthma (continued). "Polymorphic forms of GSTP1-1 correlate with the aggravation of asthma symptoms induced by air pollution, and increased risk of asthma associated with acetaminophen and exercise." (PMID 27540362, 2016). "Previous literature has shown that people carrying at least one Val allele in GSTP1 have an enhanced risk of allergic sensitisation, asthma, wheeze and impaired lung function, when exposed to TRAP." (PMID 27043549, 2016). "This trend was particularly notable in children carrying the GSTP1 genotype AA, which has been associated with an increased risk for asthma." (PMID 26490046, 2015). "Active GSTP1 variant proteins produced by the GSTP1 gene play a role in xenobiotic metabolism and influence susceptibility to asthma and other diseases." (PMID 26490046, 2015). "We investigated the effect of dietary antioxidant intake and ETS on the presence of asthma symptoms according to GSTP1 polymorphism in children age 7–12 years." (PMID 26490046, 2015). "Polymorphisms in genes related to oxidative stress (NQO1, GSTM1, and GSTP1) have been associated with increased risk of asthma." (PMID 24465030, 2014). "Association between air pollution and asthma and wheezing stratified by GSTP1 genotypes in single pollutant model." (PMID 23357926, 2013). "Association between air pollution and asthma and persistent wheezing stratified by GSTP1 genotypes in two-pollutant models." (PMID 23357926, 2013). "In the present study, we elaborated the effect modification relations between exposure to air pollution and GSTP1 on the risk of asthma and wheezing in school children, focusing on PM2.5, and ozone (O3)." (PMID 23357926, 2013). "When stratified according to proximity to pulp and paper industries there were also two haplotype blocks located in two genes (EPHX1 and GSTP1) that were associated to asthma before correction." (PMID 23066387, 2012). "The tightly linked GSTP1 SNPs rs1871042 C/T and rs947865 C/A were associated with a lower odds of asthma." (PMID 21320344, 2011). "An interaction has been demonstrated between glutathione-S-transferase P1 (GSTP1) gene polymorphism and outdoor air pollution on asthma among schoolchildren in Taiwan." (PMID 19371435, 2009). "One of the alleles encoding GSTP1, Ala114Val, was associated with asthma, OR 2.1 (95% CI 1.4 to 3.3) and the TNF-308 allele with sensitization, OR 1.6 (95% CI 1.1 to 2.2)." (PMID 19371435, 2009). "Previous interaction studies support the role of GSTP1 variants modifying the effect of exposure to air pollutants and tobacco smoke with respect to asthma and allergy." (PMID 18709160, 2008). "A functional sequence variant in GSTP1 at codon 105 (Ile105Val) has been associated with asthma and susceptibility to the adverse effects of tobacco smoke and ambient air pollution in several studies." (PMID 18335111, 2008). "Because the haplotype associations involved the GSTP1 Ile105Val SNP, we then investigated the relationship between the Ile105Val variant, in utero exposure to maternal smoking and asthma/wheezing outcomes." (PMID 18335111, 2008). "GSTP1 is located on chromosome 11q13, a previously suggested candidate region for asthma, bronchial hyperresponsiveness, and asthma-associated quantitative traits in some linkage studies." (PMID 18335111, 2008). "Although evidence indicates a role of the GSTP1 Ile105Val variant in asthma, the effect of other common variants in GSTP1 coding and promoter region and the joint effects with tobacco-smoke exposure have yet to be fully determined." (PMID 18335111, 2008). "In a study by Yu-Fen Li, it was reported that the mutation at rs1695 locus of GSTP1 gene increases the risk of childhood asthma and wheezing, and may exacerbate adverse reactions to tobacco exposure in children." (PMID 40433469, 2025). "The AG and GG genotypes, the G allele, at GSTP1 gene rs1695 locus increase the risk of asthma." (PMID 40433469, 2025).
asthma (continued). "The GC haplotype composed of GSTP1 gene rs1695 and rs4891 may pose a risk for childhood asthma [P = 0.025, OR = 2.12 (1.09–4.10)], while the AT haplotype may be protective [P = 0.025, OR = 0.47 (0.24–0.92)]." (PMID 40433469, 2025). "The genotype GC, composed of GSTP1 gene rs1695 and rs4891, may represent a risk genotype for childhood asthma, whereas genotype AT may represent a protective genotype for childhood asthma." (PMID 40433469, 2025). "Genotypic GC composed of rs1695 and rs4891 in the GSTP1 gene may represent a risk haplotype for childhood asthma, while genotypic AT may represent a protective haplotype for childhood asthma." (PMID 40433469, 2025). "Another study found evidence for a three-way interaction in school-aged children with GSTP1 homozygous Ile genotypes and low vitamin A levels who had an increased risk of asthma diagnosis (OR 4.44, 95% CI 1.58, 12.52) compared to children who did not have these two risk factors." (PMID 36250015, 2022). "Another study reported that children carrying GSTP1 rs1138272 minor alleles might represent a susceptible population with increased risk of asthma associated with air pollution." (PMID 31528233, 2019). "NO2 associated risk of asthma was increased by the GSTP1 variants, rs1138272 or rs1695." (PMID 31796815, 2019). "The GSTP1 gene is positioned in the chromosome 11q13 whereas the polymorphisms of GSTP1 gene act as danger elements for asthma disease especially four alleles such as GSTP1A (Ile105–Ala114) GSTP1B (Val105–Ala114), GSTP1C (Val105–Val114) and GSTP1D (Ile105–Val114)." (PMID 30872977, 2019). "Several reports showed that GSTP1 genotypes were associated with asthma." (PMID 27776186, 2016). "In the case of GSTP1-1, both down- and up-regulations of GSTP1-1 levels have been reported in association with asthma: whereas low levels could contribute to asthma, oxidative stress associated with the allergic response could induce GSTP1-1 expression." (PMID 27540362, 2016). "Therefore, we investigated the influence of interactions between ETS, dietary antioxidant intake, and the GSTP1 gene on risk for childhood asthma." (PMID 26490046, 2015). "Additionally, the AA GSTP1 polymorphism was associated with an increased risk for asthma in children who were exposed to ETS and had a low dietary intake of vitamin A and carotene." (PMID 26490046, 2015). "Our findings suggest that children with variant GSTP1 genotypes may constitute a susceptible population at increased risk of asthma associated with air pollution." (PMID 24465030, 2014). "GSTP1 (rs1138272 and rs1695) minor allele carriers may be a susceptible population at increased risk of asthma in association with air pollution." (PMID 24465030, 2014). "Asthma was associated with GSTP1 rs1138272 in the study population." (PMID 24465030, 2014). "Our findings support the present the gene-pollution interaction or effect modification between exposure to air pollutants (PM2.5 and O3) and GSTP1 variants, especially the isoleucine (Ile)/valine (Val) polymorphism at amino acid position 105 with respect to childhood asthma/wheezing." (PMID 23357926, 2013). "Additionally, in a study where the results of GWAS were combined with a candidate gene approach, polymorphisms in GSTP1 also showed an effect on asthma susceptibility." (PMID 22432035, 2012). "Chromosome 11 haplotype CTACGAGGCC (corresponding to MS4A2 rs574700, rs1441586, rs556917, rs502581, rs502419 and GSTP1 rs6591256, rs17593068, rs1695, rs1871042, rs947895) was associated with a nearly five-fold increase in the odds of asthma (Odds Ratio (OR) = 4.8, p = 0.007)." (PMID 21320344, 2011). "The chromosome 11 haplotype CTACGAGGCC (corresponding to MS4A2 rs574700, rs1441586, rs556917, rs502581, rs502419 and GSTP1 rs6591256, rs17593068, rs1695, rs1871042, rs947895) was associated with a nearly five-fold increase in the odds of asthma (OR = 4.8, p = 0.007)." (PMID 21320344, 2011).
asthma (continued). "EPHX1 and GSTP1 variants affect the risk of asthma in children exposed to traffic exhaust." (PMID 19371435, 2009). "DNA sequence variants in the GSTP1 locus may contribute to susceptibility to oxidative stress and airway inflammation, which are key processes in asthma pathogenesis." (PMID 18335111, 2008). "Our finding that a potentially functional SNP located in the promoter region of GSTP1 is associated with asthma is novel and suggests that transcriptional regulation may be important in asthma development." (PMID 18335111, 2008). "We found that DNA sequence variants in both the promoter and coding regions of the GSTP1 locus may contribute to the occurrence of childhood asthma and wheezing." (PMID 18335111, 2008). "To further investigate the effect of common GSTP1 variants to asthma occurrence and susceptibility to tobacco smoke, we examined associations between common GSTP1 haplotypes, tobacco-smoke exposure, childhood asthma, and related symptoms among participants in the Children’s Health Study." (PMID 18335111, 2008). "In summary, the GSTP1 locus is associated with asthma and wheezing outcomes in children." (PMID 18335111, 2008). "This study was designed to investigate whether sequence variations in the GSTP1 coding and promoter regions are associated with asthma and wheezing outcomes and to determine whether variants affect susceptibility to maternal smoking." (PMID 18335111, 2008). "Variants in both the promoter and coding regions of the GSTP1 locus may contribute to the occurrence of childhood asthma and wheezing and may increase susceptibility to adverse effects of tobacco-smoke exposure." (PMID 18335111, 2008). "We assessed whether polymorphisms of GST genes (GSTM1, GSTT1, and GSTP1) are associated with asthma and atopy among Tunisian children." (PMID 17497028, 2007). "The GSTP1 105Val allele was found to be protective against asthma and BHR." (PMID 17217536, 2007). "Therefore we intend to design this work with speculation that GSTP1 polymorphism has a role to play in asthma related phenotype." (PMID 30872977, 2019). "Another paper evaluated whether potential effects of traffic-related pollutants on doctor-diagnosed asthma, wheezing symptoms and sensitization were modified by polymorphism in genes encoding glutathione S-transferase P1 (GSTP1) and tumour necrosis factor (TNF)." (PMID 19371435, 2009). "Binary logistic regression analysis of associations between SNPs of GSTP1, HMOX1, CAT, EPHX1 gene and asthma." (PMID 40433469, 2025). "The combination of GSTP1 gene rs1695 and CAT gene rs7943316 constitutes the optimal model for predicting the risk of childhood asthma in the Fuzhou region." (PMID 40433469, 2025). "Several asthma-related genes were identified: detoxification enzymes (Cyp2a5, Gsto1, Gstp1, Gstm1, and Aldh1a1) were downregulated while Hmgb1 (alarmin) was upregulated." (PMID 35627266, 2022). "One study investigated a dose-response relationship between GSTM1, GSTP1 genotypes, another respiratory inflammatory biomarker, Clara Cell secretory protein-16, (CC16) and asthma risk." (PMID 36250015, 2022). "The genotype combinations GSTT1 ∗ GSTP1 rs762803 and GSTM1 ∗ EPHX1 rs2854450 were also associated with diisocyanate-induced asthma." (PMID 35186174, 2022). "Isocyanate-induced asthma is associated with the GSTM1 null genotype in Caucasians, and the GSTP1 Val/Val genotype is less frequent in asthmatics exposed to TDI for 10 or more years." (PMID 35186174, 2022). "A study of workers with SIC-confirmed diisocyanate-induced asthma (n = 95) revealed that the GSTM1 null and GSTP1 rs762803 genotypes were risk variants." (PMID 35186174, 2022). "The GSTP1 slow activity genotype has been found mainly to be protective for the development of asthma." (PMID 31649932, 2019).
asthma (continued). "Recent studies have also shown that Nrf2-driven GST is a possible marker for asthma susceptibility in humans: the homozygous GSTM1-null genotype increases the risk for asthma, but homozygous GSTP1 expression can protect against asthma." (PMID 30728889, 2019). "Increased risk between GST genotypes and development of asthma, BHR, wheezing or IgE mediated inflammation and even an additive effect of GSTT1 and GSTP1 low activity genotypes in the development of asthma have also been suggested." (PMID 31649932, 2019). "Children with AA at nucleotide 1695 in GSTP1 who had been exposed to ETS and a low vitamin A intake have an increased risk of asthma diagnosis (aOR, 4.44; 95 % CI,1.58–12.52) compared with children who had not been exposed to the two risk factors." (PMID 26490046, 2015). "Several studies report that GSTP1 genotypes modulate the effect of environment-induced respiratory symptoms and asthma in children." (PMID 26490046, 2015). "This was the first study to assess how ETS, low dietary vitamin A intake, and GSTP1 genotype affect asthma symptoms in children." (PMID 26490046, 2015). "GSTP1 and TNF gene variants and associations between air pollution and incident childhood asthma: the traffic, asthma and genetics (TAG) Study." (PMID 24465030, 2014). "Our previous study suggested an interaction between GSTP1 and outdoor air pollution on childhood asthma." (PMID 23357926, 2013). "Taiwan Children Health Study (TCHS) offers an opportunity to investigate the joint effects of ambient air pollution exposure and GSTP1 on childhood asthma and wheezing." (PMID 23357926, 2013). "To assess the joint effect of air pollutants and GSTP1 on asthma/wheezing, we conducted a nationwide cross-sectional study of 3,825 children in Taiwan Children Health Study." (PMID 23357926, 2013). "Three previous studies from Southern California, Cincinnati, and Stockholm have elaborated the effect of exposure to outdoor air pollutants on childhood asthma/wheezing appears to be modified by GSTP1." (PMID 23357926, 2013). "A three-way gene-gene interaction was elucidated between the gene coding glutathione S-transferase P (GSTP1), the gene coding interleukin-4 receptor alpha chain (IL4Ra) and the gene coding insulin induced gene 2 (INSIG2) on the risk of lifetime asthma." (PMID 22355322, 2012). "Among the cross-referenced genes were several known to be high priority candidate genes in both asthma and hypersensitivity, including GSTP1, ADAM33 and ADRB2." (PMID 23190421, 2012). "This study evaluated 8 of these genes (IL4, IL13, TNF-α, HLA-DRB1, HLA-DQB1, FCER1B/MS4A2, CD14, ADAM33) as well as 3 glutathione-s-transferase genes (GSTM1, GSTP1, and GSTT1) for association with asthma/allergy among urban-residing African Americans." (PMID 21320344, 2011). "Statistically significant associations were only observed for the asthma phenotype, for SNPs in GSTM1, MS4A2, and GSTP1, after correction for multiple testing." (PMID 21320344, 2011). "Statistically significant associations with asthma were observed for SNPs in GSTM1, MS4A2, and GSTP1 genes, after correction for multiple testing." (PMID 21320344, 2011). "GSTP1 AGATA (OR = 0.28, p = 0.027) and GSTP1 AGGCC (OR = 2.23, p = 0.018) displayed contrasting associations with asthma." (PMID 21320344, 2011). "The overall evidence is consistent with a complex age-dependent role in the pathogenesis of asthma and wheezing for the GSTP1 Ile105Val SNP, which affects enzyme function." (PMID 18335111, 2008). "Interaction between GSTP1 and GSTM1 has been reported for xenobiotic enhancement of allergic responses and on childhood asthma risk." (PMID 18335111, 2008). "In the SNP-based analysis, the four GSTP1 SNPs jointly explained a statistically significant portion of the occurrence of lifetime asthma and wheezing occurrences." (PMID 18335111, 2008).